INS (insulin)
Diseases named in the same sentence as INS in open-access papers (continued):
Sharing a sentence is not in itself a finding about the gene and the disease.
Hyperglycemia (continued). "However, a month later, she was converted to basal-bolus insulin therapy during a visit to the emergency department with symptoms of dizziness and dehydration due to hyperglycemia." (PMID 39329041, 2024). "Interestingly, both c-peptide and insulin co-exist in the secretory granules of β-cells in equal ratios, and both are secreted together when the cell is stimulated by hyperglycemia." (PMID 39337311, 2024). "The increased reactivity of platelets in diabetic patients, however, is attributed to multiple factors, including hyperglycemia, hyperlipidemia, resistance to insulin and a more pronounced inflammatory and oxidative status along with increased expression of glycoprotein receptors and growth factors." (PMID 39125606, 2024). "Therefore, the main aim of this study was to investigate the NFκB and Nrf2 expression in the myenteric ganglia and its muscular environment in different gut segments of diabetic rats with untreated chronic hyperglycaemia and insulin treatment." (PMID 39457659, 2024). "GLP1-RAs are incretin medications that increase the production of glucose-dependent insulin, suppress the release of glucagon from pancreatic α cells in hyperglycemia states, diminish the stomach’s emptying, and affect appetite, resulting in a decrease in food consumption." (PMID 39768947, 2024). "When the liver is insulin resistant, the inhibitory effects of insulin are impaired whereas the stimulatory effect of the hormone on lipogenesis remains intact, contributing to the development of hyperglycemia and hepatic steatosis." (PMID 38981607, 2024). "The Active Peptide from Shark Liver (APSL) and S-8300, hepatic functional peptides isolated from shark species, were found to lower hyperglycaemia in diabetic mice, increasing insulin secretion and sensitivity, repairing lesions to pancreatic islets, and having a hypolipidemic effect." (PMID 38786601, 2024). "In conclusion, the successful rescue effects of the anti‐hyperglycemic drugs validated further that the tt‐DDE phenotype involving insulin resistance, mild postprandial hyperglycemia and sustained alteration of lipid metabolisms resulted in the microvascular phenotype observed." (PMID 38059818, 2024). "Therefore, this need for treatment with insulin can be considered an indicator of the severity of hyperglycemia." (PMID 38618305, 2024). "Vitamin D may increase insulin secretion and sensitivity and improve β-cell function, thus reducing hyperglycemia and oxidative stress, major nerve damage factors." (PMID 38592202, 2024). "Indeed, the data show that, compared to those under RC, patients under DEC received significantly more rapid acting insulin in response to hyperglycemia, specifically in cases when BG measured over 200 mg/dL." (PMID 39451871, 2024). "Alternatively, the absence of FOXA1 may affect the development and maturation of pancreatic β-cells, inhibiting insulin secretion and leading to hyperglycemia." (PMID 38605023, 2024). "However, there is still an unmet need for adjunctive treatments other than insulin therapy to address the twin challenges of managing hyperglycaemia and hypoglycaemia in diabetic dogs." (PMID 38686463, 2024). "Insulin injection corrects both hyperglycemia and DN in T1D patients." (PMID 38212312, 2024). "β-cells’ dysfunction results in a relative lack of insulin secretion, which causes the development of hyperglycemia or T2D." (PMID 36904097, 2023). "Moreover, O304 preserved β-cell function in an in vivo insulin resistant context and under in vitro conditions of chronic hyperglycemia." (PMID 37626210, 2023). "Although several studies have demonstrated that GPR43 activation improves hyperglycemia and IR in T2D mice, there was also evidence that GPR43-deficient mice fed a high-fat diet (HFD) improved glucose tolerance and impaired insulin signaling." (PMID 36891383, 2023).
Hyperglycemia (continued). "However, it is increasingly thought that in most subjects, a relative decrease in insulin secretion is the final event that leads to hyperglycaemia." (PMID 37759802, 2023). "Studies in healthy pregnancies, with mild untreated hyperglycemia (HAPO) or GDM have found a positive association between cord blood insulin and/or C-peptide and birth anthropometry, but they did not adjust for cord blood HDL." (PMID 37056671, 2023). "Consequently, the combination of hyperglycemia and oxidative stress leads to a decrease in insulin biosynthesis and secretion, thereby perpetuating a vicious cycle of sustained hyperglycemia." (PMID 37958572, 2023). "Hyperglycemia, or elevated blood glucose, can result from chronic metabolic conditions as well as acute stress and reflects the inability of the body to produce or effectively use insulin." (PMID 36877063, 2023). "In response to hyperglycaemia, there are reductions in regional cerebral blood flow and increases in insulin that facilitate glucose clearance and may result in the sitting‐induced reductions in cerebral reactivity that we report." (PMID 37731204, 2023). "Similarly, mice with LRP5-mutant (gain-of-function) and insulin-dependent spontaneous hyperglycaemia displayed better bone health with increased insulin sensitivity." (PMID 37569816, 2023). "Incorrect administration timing may lead to either hypo or hyperglycaemia, even when the amount of insulin effectively ‘matches’ the carbohydrates." (PMID 37132569, 2023). "Today, researchers are studying safe and effective drugs to overcome the destructive effects of insulin-related metabolic disorders, including hyperglycemia, hyperinsulinemia, hyperlipidemia, oxidative stress, inflammation, atherosclerosis, and other complications." (PMID 37153436, 2023). "In cases of persistent hyperglycemia despite insulin administration, prolonged hospitalization with insulin infusion might be required." (PMID 37854477, 2023). "An emerging body of evidence suggests that insulin may suppress the inflammatory process, through preventing hyperglycemia and by modulating several different inflammatory molecules." (PMID 37834819, 2023). "It is recommended that wherever indicated, treatment with insulin should not be delayed as in case of marked weight loss, severe hyperglycemia and where there are contraindications to use oral hypoglycaemics." (PMID 36694770, 2023). "STZ induces hyperglycemia through cytotoxic effects on insulin-producing beta cells." (PMID 36877063, 2023). "Under normal conditions, β cells are inactive in secreting insulin during fasting period, and postprandial transient hyperglycemia can stimulate β cells to enhance glucose‐stimulated insulin secretion (GSIS), thereby increasing the blood insulin to meet the demands for lowering blood glucose." (PMID 37303813, 2023). "The complementary effects of the combination of GLP-1 RA with basal insulin, lowering both postprandial and fasting hyperglycemia, may lead to narrowing GV for this combination strategy." (PMID 36897731, 2023). "It is worth noting that KPD patients, after several months of initial short-term intensive insulin therapy to correct hyperglycemia, beta cell function will gradually recover from the initial decompensated state, with significant improvements in insulin sensitivity." (PMID 38027130, 2023). "Moreover, low expression levels of IGFBP-2 at the adipose tissue mRNA and its circulating protein levels are connected to hyperglycemia and hypertriglyceridemia and positively correlate with insulin sensitivity." (PMID 37891752, 2023).
Hyperglycemia (continued). "While shorter, poorer sleep may lead to deteriorating glycemic control through various mechanisms, hyperglycemia may also lead to poor sleep by way of increased nocturnal voiding, thirst, and need for overnight insulin injections." (PMID 40303250, 2023). "Reduced insulin response may be due to a variety of factors, including lipotoxicity, mitochondrial dysfunction, ER stress, hyperglycemia, and inflammation." (PMID 36902218, 2023). "In inpatients with hyperglycaemia, the best corrective treatment is insulin." (PMID 38068834, 2023). "The researchers hypothesize that the increased antioxidant capacity in the diet-controlled GD group may be because the group had a more balanced diet compared to the insulin-controlled and NG group, potentially due to the fear of hyperglycemia or hypoglycemia." (PMID 37107217, 2023). "The decline in insulin sensitivity is the main reason for the development of hyperglycemia." (PMID 37110134, 2023). "Basal insulin is a convenient and effective option in the majority of patients, provided the risk of post-meal hyperglycemia is not elevated significantly." (PMID 36624650, 2023). "Predicting insulin need could help stratify the hyperglycemia severity for patients with gestational diabetes and could be a starting point for healthcare settings to assign resources towards a more rational allocation in situations of limited capacity." (PMID 37268897, 2023). "Patients with NAFLD may have hyperlipidemia, hyperglycemia, hyperinsulinemia, and decreased insulin sensitivity on a biochemical level." (PMID 36938188, 2023). "In addition, phenolic acid inhibits the rapid absorption of glucose, thereby decreasing postprandial hyperglycaemia, enhancing insulin release, activating insulin receptors, and modulating glucose release from the liver." (PMID 36677591, 2023). "Our findings suggest that patients treated with insulin (when associated with metformin or sulfonylurea) and sulfonylureas (with or without DPP4i associated) were exposed to a higher risk of hyperglycemia at admission." (PMID 36830792, 2023). "In a socially deprived suburb of Paris, we selected women who delivered between 01/01/2012 and 31/12/2018 and received care (nurse, dietician, diabetologist evaluation, advice, regular follow-up to adjust insulin doses if requested) for hyperglycemia in pregnancy." (PMID 37853313, 2023). "Diets high in GI or glycemic load (GL) have been hypothesized to elevate postprandial glucose and insulin responses, leading to insulin resistance and hyperglycemia." (PMID 37375723, 2023). "The upregulation of microtubule clustering in DN may be due to prolonged hyperglycemia, resulting in compensatory upregulation of microtubule clustering and increased insulin secretion." (PMID 37513479, 2023). "The presence of metabolic stress in the mSTZ model β-cells after clearance of the chemical stressor can be explained by the surviving population of β-cells being too small to prevent hyperglycemia and hence leading to compensatory insulin-production behavior and subsequent stress." (PMID 37697055, 2023). "This response reduces sensitivity to insulin, promotes hyperglycemia, and stimulates proteolysis." (PMID 36808704, 2023). "Acute complications result from uncontrolled blood glucose levels that are too high (hyperglycemia) or too low (hypoglycemia), which might be due to mismatching the required need for insulin." (PMID 36835260, 2023). "The main biological effects of taurine comprise antioxidant activity by inhibiting mitochondrial reactive oxygen species generation, glucose homeostasis by interfering the insulin-signaling pathway and osmoregulation due to counteracting hyperglycemia-induced osmotic imbalance." (PMID 37623889, 2023).
Hyperglycemia (continued). "As the beta-cell function starts to fail but has not completely failed, due to the mitigated hyperinsulinemia, the insulin sensitivity gradually increases, which pauses the progression of the ultimate hyperglycemia and improves the glucose level from 151 mg/dl to 117 mg/dl." (PMID 36848379, 2023). "Noteworthy, the inhibition of DPPIV catalytic activity in Hep3B cells is synergistic, indicating that the mixture of these phytochemicals can counteract the establishment of a hyperglycemia condition and can inhibit the molecular pathways of insulin resistance that lead to T2DM development." (PMID 37175783, 2023). "The plasma concentration change of most metabolites after the glucose load was mainly associated with indices of hyperglycemia rather than insulin resistance, insulin secretion, or BMI." (PMID 36677056, 2023). "Even though hyperglycemia could be controlled by drug administration or exogenous insulin, these treatments are unable to provide regulation of blood glucose." (PMID 36677212, 2023). "In cases of sustained hyperglycemia, the insulin dose may be escalated in gradual increments of 10%." (PMID 38068755, 2023). "BCAAs were often elevated in hyperglycemia, and it was widely demonstrated that BCAAs upregulated glucose transporters and activated insulin secretion, although the mechanism responsible for the increased BCAAs in these insulin-resistant hyperglycemic conditions is not completely clear." (PMID 38139131, 2023). "Reduction in basal insulin dose might promote hyperglycemia at multiple points during the day (especially for patients using long- or ultra-long-acting insulin)." (PMID 36981876, 2023). "Hyperglycemia was managed and glycemic targets were achieved with dietary modifications in 41 (25%); 115 women required additional metformin (69%), and in only a minority of the cohort, both metformin and insulin were needed (11/167; 7%)." (PMID 37289757, 2023). "Therefore, insulin infusion can rapidly correct complications arising from hyperglycemia, including adhesion molecules and lipid peroxidation." (PMID 37048638, 2023). "SeNP and/or BV treatments improved the deleterious effects induced with STZ administration by improving the serum insulin concentrations, which resulted in decreasing the hyperglycemia, decreasing the serum BUN, creatinine and CRP while increasing the serum albumin concentrations." (PMID 36984840, 2023). "Moreover, hyperglycemia promotes increased insulin production leading to vascular stenosis, increased vascular resistance, and high blood pressure." (PMID 37008898, 2023). "Diabetes mellitus is a metabolic syndrome characterized by hyperglycemia, and it is caused by a disturbed metabolism because of the ingested food, resulting in a lack of insulin secretion or insulin resistance." (PMID 37389344, 2023). "The transient hyperglycemia after COVID-19 vaccination may be explained by vaccine-induced immunological reactions and the production of anti-insulin hormones, such as cortisol, catecholamines, etc.." (PMID 38140151, 2023). "The higher number of pump engagements are likely indicative of the user's reactive attempts to monitor and mitigate hyperglycemia by checking glucose levels and giving correction boluses of insulin (which was also predictive of lower TIR in the same-day analysis)." (PMID 37614410, 2023). "However, in S961 treated animals, senolysis significantly increased hyperglycemia suggesting that in the setting of extreme insulin resistance, targeting senescent cells is counterproductive." (PMID 36640267, 2023). "Activation of PPARγ by TZDs improves hyperglycemia and insulin sensitivity in patients with T2DM." (PMID 36836874, 2023). "A prospective study concluded that hyperglycemia is significantly associated with the risk of an extended hospitalization due to asthma exacerbation, regardless of the route of insulin administration." (PMID 37056543, 2023). "After the detection of hyperglycaemia, insulin therapy was needed in two cases." (PMID 36835446, 2023).
Hyperglycemia (continued). "Thus, depending on the experimental conditions, fetal exposure to hyperglycemia manifests in juvenile rodent offspring with varying phenotypes for adiposity, glucose tolerance, and insulin sensitivity." (PMID 36717684, 2023). "GDM is characterized by an inadequate glucose dependent insulin secretion leading to hyperglycemia." (PMID 37079606, 2023). "Toxicity to the pancreas includes interactions of ASP with insulin and may lead to insulin-dependent hyperglycemia." (PMID 38067249, 2023). "It should be noted that pre-competition insulin reduction may have contributed to pre- and post-competition hyperglycemia, though other factors, such as competition-related stress, may have influenced the athlete’s BG before and after racing." (PMID 37999431, 2023). "So, hyperglycemia is a necessary, bur insufficient agent, stimulated hepatic insulin synthesis." (PMID 38019818, 2023). "The findings of the present in vivostudy clearly demonstrate that antioxidant vitamins (C and E), reduce hyperglycemia and hyperinsulinemia by upregulating GSK 3β and FOXO1 proteins involved in glucose metabolism and insulin signaling caused by glyphosate exposure." (PMID 38274944, 2023). "Thus, the treatment of hyperglycemia should target not only impaired insulin secretion but also hepatic and muscular insulin resistance, reduced intestinal incretin effects, and increased glucose renal threshold." (PMID 37626624, 2023). "It has also been concluded that activation of ATP-sensitive potassium channels by isoflurane in pancreatic β-cells could impair both insulin secretion and glucose tolerance resulting hyperglycemia-generated decrease in alleviating influences of isoflurane." (PMID 36750771, 2023). "Management of hyperglycemia in neonates with subcutaneous insulin is challenging because of frequent feeding, variable quantity of milk intake with each feed, low insulin dose requirements, and high risk for hypoglycemia and associated complications in this population." (PMID 37664823, 2023). "The blunting of glucose uptake and insulin action by adipokines further aggravates hyperglycemia." (PMID 36895277, 2023). "In 1952, Professor Jorgen Pedersen hypothesized that maternal hyperglycemia would lead to fetal hyperglycemia, thereby stimulating insulin overproduction in the fetus to maintain normal glycemia." (PMID 37960204, 2023). "In addition, the increased inflammation seen with COVID-19, as well as treatment of COVID-19 with steroids can worsen a patient’s hyperglycemia thereby requiring increased insulin dosages." (PMID 37478111, 2023). "This vicious cycle continues until pancreatic beta-cell activity can no longer match the increased insulin demand caused by insulin resistance, resulting in hyperglycemia." (PMID 37346347, 2023). "Here, we discovered that DM-induced inflammation, hyperglycemia, and insulin dysregulation may disrupt synaptic function and impair learning and memory." (PMID 37701028, 2023). "Insulin treatment reversed the salivary spectra observed in patients with hyperglycemia." (PMID 37373896, 2023). "Insulin should be the main treatment in the case of stress-induced hyperglycemia." (PMID 37187644, 2023). "While this strategy helps manage T1D, under and overdosing on exogenous insulin may lead to hyperglycemia and hypoglycemia, respectively, leading to long‐term morbidity." (PMID 37476069, 2023). "However, measuring glucose is an indirect method for calculating the required insulin dosage and failure to administer the correct amount of insulin can lead to severe hypoglycaemia or hyperglycaemia with serious consequences to health." (PMID 37504117, 2023). "DM comprises metabolic disorders characterized by hyperglycemia related to inadequate insulin production or improper response of the cells to insulin, and the major complications include poor wound healing, cardiovascular diseases, retinopathy, and nephropathy." (PMID 36737813, 2023).